CD209 (CD209 molecule)
Diseases named in the same sentence as CD209 in open-access papers (continued):
Sharing a sentence is not in itself a finding about the gene and the disease.
Kawasaki disease (5 papers, 2012 to 2025). A rare inflammatory disease characterized by an acute febrile, systemic, self-limiting, medium-vessel vasculitis primarily affecting children. "In addition, significant associations were found between high risk of Kawasaki disease with CD209 polymorphisms rs4804800 and rs2287886." (PMID 33101356, 2020). "Genotype and allele frequencies of the CD209 gene in controls and patients with Kawasaki disease." (PMID 25148534, 2014). "Genotype and allele frequencies of the CD209 gene in patients with Kawasaki disease responding or not responding to intravenous immunoglobulin treatment." (PMID 25148534, 2014). "Genotype and allele frequencies of CD209 gene in patients having Kawasaki disease with or without coronary artery lesion formation." (PMID 25148534, 2014). "Haplotype frequencies of the CD209 gene in controls and patients with Kawasaki disease." (PMID 25148534, 2014).
nasopharyngeal carcinoma (5 papers, 2010 to 2024). A carcinoma arising from the nasopharyngeal epithelium. "In nasopharyngeal carcinoma, the interaction between tumor cells and ANXA2 can activate dendritic-cell-specific ICAM-grabbing non-integrin (DC-SIGN), also known as CD209." (PMID 39057791, 2024).
osteosarcoma (5 papers, 2020 to 2025). A usually aggressive malignant bone-forming mesenchymal neoplasm, predominantly affecting adolescents and young adults. "Next, we determined the expression levels of CD209 (another M2 macrophage marker) in osteosarcoma tissues from K7M2 WT orthotopic transplantation through an immunofluorescence assay." (PMID 35889217, 2022). "Gene expression analysis and CD209 staining also confirmed the enrichment of M2 macrophages in human osteosarcoma tissues." (PMID 33363016, 2020).
periodontitis (5 papers, 2015 to 2023). An acute or chronic inflammatory process that affects the tissues that surround and support the teeth. "Expansion of blood myeloid CD1c+(BDCA-1) CD209+ DCs is reported in peripheral blood of periodontitis patients; moreover, this expansion further increases 24 h after mechanical debridement (scaling and root planning), which provokes a bacteremia." (PMID 37764988, 2023). "P. gingivalis mfa-1 targets CD209 for entry into DCs and promotes survival within these cells, and the number of CD209+ DCs circulating in the periphery increase during periodontitis." (PMID 36873050, 2023). "Moreover, postmortem analysis of coronary artery samples from periodontitis patients who had coronary artery disease shows co-localization of CD209 (DC-SIGN), myeloid DCs marker, with P. gingivalis minor fimbria protein (mfa-1) in the atherosclerotic plaques." (PMID 37764988, 2023).
Sepsis (5 papers, 2017 to 2024). Sepsis is defined as life-threatening organ dysfunction caused by a dysregulated host response to infection. "Although human CD209+ macrophages have been described as having enhanced phagocytosis in the context of sepsis and are thus probably associated with enhanced protective immunity, we did not detect any IL12 mRNA expression (the key cytokine qualifying M1 antitumour macrophages) in E-MpMs." (PMID 30510965, 2018). "One SNP was validated to be related to the occurrence of sepsis in both cohorts: DC-SIGN (CD209) rs4804800." (PMID 38982248, 2024). "The ASC-mediated increase of CD206, CD209, and CD163 on the surface of Mphs and mDCs suggests an enhanced ability to clear a range of blood-borne pathogens, supporting a therapeutic potential in infection-mediated diseases such as sepsis." (PMID 33138862, 2020). "We found profound decrease of MO→iDC in the humanized mice 28 days after sepsis, demonstrated by depressed expression of CD1a, CD83, and CD209, diminished production of IL-12p70, and depressed ability to stimulate T cells in mice after CLP as compared to SHAM or CONTR." (PMID 28507543, 2017).
atopic dermatitis (4 papers, 2020 to 2023). "Previously, a reduction of CD209+ dendritic cells in human skin from atopic eczema patients was found associated with clinical improvement." (PMID 32556497, 2020). "Increased expression of the CD209 gene has also been observed in skin biopsies from German shepherd dogs with atopic dermatitis and a relationship between this CD209 protein and inflammation has been suggested." (PMID 35355298, 2022).
Dengue hemorrhagic fever (4 papers, 2011 to 2019). A serious condition caused by Dengue virus infection. "The rs4804803 SNP (G) in the cluster of differentiation 209 (CD209) [(encodes Dendritic Cell-Specific Intercellular adhesion molecule-3-Grabbing Non-integrin (DC-SIGN)) promoter region could contribute to the pathogenesis of dengue hemorrhagic fever (DHF) in Thai and Taiwanese populations." (PMID 30759739, 2019).
influenza (4 papers, 2015 to 2025). An acute viral infection of the respiratory tract, occurring in isolated cases, in epidemics, or in pandemics; it is caused by serologically different strains of viruses (influenzaviruses) designated A, B, and C, has a 3-day incubation period, and usually lasts for 3 to 10 days. "Previous study has shown that DC-SIGN (CD209) and L-SIGN (CD209L) are endocytic receptors for influenza viral entry." (PMID 39846844, 2025).
lung carcinoma (4 papers, 2016 to 2025). "Previous studies showed that ACE2 and CD209 were overexpressed in the healthy lungs of smokers, especially former smokers, but the relevance of this phenomenon in lung cancer remains unclear." (PMID 35783255, 2022).
preeclampsia (4 papers, 2018 to 2022). Preeclampsia is a hypertensive disorder of pregnancy that is characterized by new-onset hypertension with proteinuria presenting after 20 weeks of gestation, and depending on mild or severe forms may initially present with severe headache, visual disturbances, and hyperreflexia. "Recently depletion or malfunction of T cell populations has been associated with recurrent spontaneous abortion and incidence of preeclampsia and higher numbers of CD209+ and CD83+ DC have been reported in the preeclamptic placental bed." (PMID 30949130, 2019).
sarcoidosis (4 papers, 2017 to 2025). Sarcoidosis is a multisystemic disorder of unknown cause characterized by the formation of immune granulomas in involved organs. "Some EV markers were common between HP and sarcoidosis (CD11c, CD1c, CD209, CD4, CD40, CD44, CD8)." (PMID 36835481, 2023). "Because sarcoidosis is notably associated with Th1/Th17 multisystem abnormity, an increased number of CD68+ CD163− M1 macrophages and CD209+ dendritic cells and a decreased number of CD68+ CD163+ M2 macrophages may be a histologic surrogate for the diagnosis of cardiac sarcoidosis." (PMID 35011991, 2022).
sarcoma (4 papers, 2016 to 2023). A usually aggressive malignant neoplasm of the soft tissue or bone. "In the TCGA dataset, we found that CD209 was expressed in various cancer types, while its mRNA abundance was highest in sarcoma (SARC), whereas the protein level of CD209 was most enriched in head and neck cancer." (PMID 35783255, 2022).
tick-borne encephalitis (4 papers, 2013 to 2025). Tick-borne encephalitis is caused by an arbovirus of the Flaviviridae family (tick-borne encephalitis virus, TBEV), transmitted principally by the bite of the Ixodes ricinus tick. "It has been shown in the Russian population that five SNPs in OAS2 and OAS3 genes, as well as two SNPs in IFNL3/IL28B gene and polymorphisms in the TLR3, CD209, and IL10 genes were associated with predisposition to severe forms of tick-borne encephalitis." (PMID 29297316, 2017).
abortion (3 papers, 2015 to 2025). the ending of pregnancy by removing a fetus or embryo before it can survive outside the uterus. "A higher M1/M2 ratio of dMφs was demonstrated in spontaneous abortion, which manifested a higher expression of M1-associated markers (CD86, CD80, and IL-1β) and lower expression of M2-associated markers (CD209, CD206, IL-10, and TGF-β1." (PMID 37033974, 2023).
acute myeloid leukemia (3 papers, 2019 to 2023). Acute myeloid leukemia (AML) is a group of neoplasms arising from precursor cells committed to the myeloid cell-line differentiation. "Likewise, we were not able to detect CD209+CD14+CD163+ ercDCs among PBMC of healthy donors or patients by flow cytometry (data not shown) and the ercDC score was very low in samples of acute myeloid leukemia of the TCGA collection compared to ccRCCs (not shown)." (PMID 36291154, 2022).
fibrosis (3 papers, 2019 to 2022). the formation of excess fibrous connective tissue in an organ or tissue in a reparative or reactive process. "The SNPs in IL17A (rs2275913), IL10 (rs1800871 and rs1800872), and CD209 (rs2287886 and rs4804803) genes were genotyped in the no fibrosis patients (classified as Niamey 1) (n = 28) and fibrosis patients (classified as Niamey 7) (n = 9)." (PMID 34970264, 2021).
glioma (3 papers, 2019 to 2025). A benign or malignant brain and spinal cord tumor that arises from glial cells (astrocytes, oligodendrocytes, ependymal cells). "CD209, associated with myeloid cells, was upregulated in these patients, suggesting a link to immune cell infiltration in gliomas." (PMID 40106404, 2025). "In particular, MG (Iba1+ CD163−) were diffusely scattered throughout gliomas, while Iba1+CD163+ BMDMs and CD206+, CD169+, and CD209+ subsets of BMDMs were found in close proximity to blood vessels in gliomas." (PMID 33374253, 2020). "CD209 and CD1A did not demonstrate significant upregulation in any of the human glioma subtypes." (PMID 31475119, 2019).
lupus nephritis (3 papers, 2017 to 2024). Glomerulonephritis in the context of systemic lupus erythematosus. "A recent study showed the expression of CD209 on podocytes and its possible role in immune and inflammatory responses in lupus nephritis." (PMID 28106835, 2017).
osteoarthritis (3 papers, 2017 to 2025). A noninflammatory degenerative joint disease occurring chiefly in older persons, characterized by degeneration of the articular cartilage, hypertrophy of bone at the margins and changes in the synovial membrane. "CD209+ cells were also higher in RA synovium than osteoarthritis synovium." (PMID 28377641, 2017). "In addition, we observed that culture of healthy CD209+ DC with IA synovial fluid (SF), but not Osteoarthritis (OA) SF, was sufficient to induce the development of CD209/CD14+ DC, leading to a poly-mature DC phenotype." (PMID 35095831, 2021).
ovarian carcinoma (3 papers, 2018 to 2024). A malignant neoplasm originating from the surface ovarian epithelium. "It has been demonstrated that the protumoral phenotype of TAMs can be mitigated by suppressing the expression of M2 phenotype markers, CD163 and CD209, in ovarian cancer A2780 cells." (PMID 38970121, 2024). "In vitro—Human monocyte cell-line THP-1-stimulated and ovarian cancer cell-lines (to produce tumor associated M2 macrophages cell-line (CD163 and CD209))." (PMID 36140188, 2022). "In addition, deoxyschizandrin was found to inhibit the expression of the M2 phenotype markers CD163 and CD209 in TAMs, macrophages stimulated by the ovarian cancer cells." (PMID 29342940, 2018).
SARS-CoV infection (3 papers, 2006 to 2025). "C-type lectin domain family 4 member L (CD209) is expressed on type II alveolar cells in human lungs, which are an important target for SARS-CoV infection, as well as on endothelial cells." (PMID 40568587, 2025).
Behçet's Disease (2 papers, 2017 to 2018). "Levels of CD209 on whole leukocytes correlate with disease severity in Behçet’s Disease." (PMID 29800237, 2018).
cervical carcinoma (2 papers, 2012 to 2022). A carcinoma arising from either the exocervical squamous epithelium or the endocervical glandular epithelium. "Transfection of cervical carcinoma epithelial (HeLa) cells with a plasmid encoding CD209, the gene encoding DC-SIGN, resulted in a marked increase in CD209 transcription levels detected by quantitative real-time PCR and significantly increased binding of live S. Typhi detected in an adhesion assay." (PMID 36286551, 2022).
Hyperglycemia (2 papers, 2021 to 2022). An increased concentration of glucose in the blood. "So, it is likely that elevated levels of TGF-β1 might play a role in the reduction of CD209 levels that have been related to hyperglycemia." (PMID 33742062, 2021).
Immunodeficiency (2 papers, 2008 to 2021). Failure of the immune system to protect the body adequately from infection, due to the absence or insufficiency of some component process or substance. "Not like the T/Mø+ subtype with activated immune factors and high expression of ACE2 and CD209, DC+, Neu+ and DC−T/Mø−Neu− subtypes may produce the high virus load by immunodeficiency." (PMID 34502134, 2021).
leukaemia (2 papers, 2019 to 2022). "For instance, it has been reported that THP-1 cells and the CD34 + (KG-1) leukaemia cell line incubated with varying concentrations of rhGM-CSF and rhIL-4 for 5 days showed upregulated levels of CD11c, CD80 and CD86 and of the cell-surface receptors CD40, CD209 (DC-SIGN) but failed to express CD83." (PMID 34800147, 2022).
Obesity (2 papers, 2025). Accumulation of substantial excess body fat. "As shown in the multivariate analysis, obesity and CD209 genotypes continued to influence disease severity." (PMID 41009975, 2025).
peanut allergy (2 papers, 2021). "In support of this model, we show clinically that the treatment of peanut allergy with OIT is associated with a decrease in CD209+ DCs, consistent with the idea that disrupting this positive feedback loop impairs the allergic immune response." (PMID 33944900, 2021).
psoriasis (2 papers, 2017). An autoimmune condition characterized by red, well-delineated plaques with silvery scales that are usually on the extensor surfaces and scalp. "One study evaluated the level of CD209 in psoriasis vulgaris lesions, and reported that CD209 was higher in psoriasis lesions compared with normal tissues." (PMID 28106835, 2017).
psoriasis vulgaris (2 papers, 2017 to 2020). Plaque psoriasis is the most common presentation of psoriasis. "The level of CD209 was higher in psoriasis vulgaris lesions than normal tissues." (PMID 28106835, 2017).
schistosomiasis (2 papers, 2021 to 2026). An infectious disease caused by parasitic trematodes of the genus Schistosoma that colonize human blood vessels and release eggs that can cause granulomatous reactions leading to acute (swimmer's itch or acute schistosomiasis syndrome) or chronic disease. "Here, we found an association between the presence of genotype AG for the CD209 rs2287886 with higher levels of IL-17 in non-stimulated PBMC supernatant when compared with the GG genotype in schistosomiasis patients." (PMID 34970264, 2021).
sickle cell anemia (2 papers, 2010 to 2015). "Genotypic and allelic frequencies of the CD209 gene promoter (rs4803803) polymorphism between African and American sickle cell disease groups." (PMID 25755928, 2015). "We also examined the diversity of CD209 (snp 336A/G) gene promoter polymorphisms between sickle cell disease and healthy control groups in Africa and United States." (PMID 25755928, 2015). "Genotypic frequencies of the CD209 gene promoter (rs4803803) polymorphism, determined among African and American sickle cell disease and control groups." (PMID 25755928, 2015). "There was an extensive and significant difference in the genotypic frequency of the CD209 mutant variant (snp 336G/G) between sickle cell disease and control populations in Africa (P = 0.002)." (PMID 25755928, 2015). "Allelic frequencies of the CD209 gene promoter (rs4803803) polymorphism, determined among African and American sickle cell disease and control groups." (PMID 25755928, 2015). "We analyzed the frequency of the CD209 gene (rs4804803) in healthy control and sickle cell disease (SCD) populations and determined association with disease." (PMID 25755928, 2015). "An additional mechanism for our observation could be that there is an increased mortality of sickle cell disease patients that are also carriers of the CD209 ‘G’ allele, especially homozygotes, and are therefore missing from the Malian SCD cohort." (PMID 25755928, 2015). "A decrease in CD209 expression in the homozygote mutant variant of DC-SIGN in sickle cell disease patients resulting in lower susceptibility to infectious stimulus, with the reverse the case among control groups with the homozygote wild type variant would be a confirmatory outcome." (PMID 25755928, 2015). "We hypothesize that CD209 mutant variants occur at a higher frequency among Africans and in sickle cell disease." (PMID 25755928, 2015). "Genotypic and allelic frequency of CD209 polymorphisms between sickle cell disease groups." (PMID 25755928, 2015). "To this end, we examined the genotypic and allelic frequency of CD209 gene promoter polymorphism (SNP-336 A/G; rs4804803) in control groups (Africans versus African Americans versus Caucasians) and between sickle cell disease populations (African versus American)." (PMID 25755928, 2015).
typhoid fever (2 papers, 2020 to 2022). A bacterial infectious disorder contracted by consumption of food or drink contaminated with Salmonella typhi. "A study by Ye and colleagues on S. typhimurium, which causes typhoid fever in mice, speculated that many interactions between CD209 and LPS core could lead to CD209 deposition at infection sites (especially during chronic infections)." (PMID 33488579, 2020).
acute respiratory distress syndrome (1 paper, 2021). Progressive and life-threatening pulmonary distress in the absence of an underlying pulmonary condition, usually following major trauma or surgery. "Moreover, we also observed such significant associations of CD209 expression with immune cell composition in blood samples of 160 Acute Respiratory Distress Syndrome (ARDS) cases and 142 non-ARDS controls, regardless of the disease status (see Methods: Blood samples from ARDS cases and controls)." (PMID 34502134, 2021).
bovine tuberculosis (1 paper, 2024). "Several of the genes downregulated in Yakutian cattle were related to the susceptibility of a host to diseases, including Mycobacterium avium paratuberculosis, bovine tuberculosis, mastitis, brucellosis, and bovine respiratory disease (CD209, EEF1A2, SLC2A1)." (PMID 39333243, 2024).
celiac disease (1 paper, 2007). An autoimmune genetic disorder with an unknown pattern of inheritance that primarily affects the digestive tract. "The CD209 gene was found to be increasing celiac disease susceptibility only in HLA-DQ2-negative patients, i.e., those lacking the main genetic susceptibility factor described to celiac disease." (PMID 18070336, 2007).
cervical squamous cell carcinoma (1 paper, 2022). A squamous cell carcinoma arising from the cervical epithelium. "We found that the reduced CD209 expression was associated with a poor overall survival rate in LUAD (p = 0.012, HR = 0.69), READ (rectum adenocarcinoma) (p = 0.052, HR = 0.46), and (cervical squamous cell carcinoma) (p = 0.034, HR = 0.52)." (PMID 35783255, 2022).
cystic fibrosis (1 paper, 2022). Autosomal recessive disorder caused by pathogenic variants in the CFTR gene (cystic fibrosis transmembrane conductance regulator), which encodes a chloride and bicarbonate channel expressed in epithelial cells, and follow the diagnosis criteria. "Ralstonia, isolated from cystic fibrosis patients, were negatively correlated with indices of antioxidant capacity (POD, T-AOC, and GSH), digestive enzymic activities (trypsin, LPS, and AKP), and anti-inflammatory capacity (IL-10 and CD209)." (PMID 35844501, 2022).
depression (1 paper, 2021). "In addition, we found that CD209 expression in lung was associated with immune related symptoms such as tiredness or low energy, depression and duration of fitness." (PMID 34502134, 2021).